ID2 (inhibitor of DNA binding 2)
Diseases named in the same sentence as ID2 in open-access papers (continued):
Sharing a sentence is not in itself a finding about the gene and the disease.
tumor (continued). "Consistent with low WNT signaling in RevCSCs, BLM tumor stem cells had decreased expression of WNT/stemness-related genes compared to Min tumors such as Axin2, Id2, Sox4, Wnt6, Wnt10a, Id3, Prox1, and Id1." (PMID 38893159, 2024). "Together, these results suggest that Id2 is required for the proliferation and effector function of tumor-infiltrating CD8+ T cells, thereby facilitating tumor eradication." (PMID 38287103, 2024). "In addition, mice that lack Id2 develop intestinal adenomas and show a hyperproliferation of colon stem cells during embryonic development due to increased Wnt/β-catenin signaling, suggesting that ID2 may function as a tumor suppressor in other cell types." (PMID 35775482, 2022). "Each of the LEP, NOTCH1, SPRY1, PPARG, ID2, and CIDEA genes is also involved in tumor development in humans." (PMID 35395810, 2022). "In particular, ID2 expression downregulated TNF-α, which induced proliferation of Tregs at the tumor site." (PMID 35806328, 2022). "The effect of toyocamycin on p21, ID2, OCT4, SOX2 and NANOG expression was also verified in the tumor sections by immunohistochemistry." (PMID 35078502, 2022). "Our data in this primary tumor model indicates a synergy between CTLA-4 blockade and Id2-kd N2a cells." (PMID 26079374, 2015). "Thus, ectopic expression of the degradation-resistant form of Id2 protein in certain tumor cell types might provide beneficial effects for displaying Id2-mediated signaling and phenotypic traits, which might easily be overlooked with transfection of wild-type Id2." (PMID 19257909, 2009). "Considering the alterations in PRMT2 that influence the transcription of ID1, ID2, and ID3, we demonstrated that PRMT2 may also regulate the tumour stemness of OSCC." (PMID 40078091, 2025). "To assess whether Id2 is necessary for the maintenance of stem-like CD8+ T cells, we adoptively transferred IL-15-primed OT-I CD8+ T cells into B16-OVA tumor-bearing B6.SJL mice and investigated the properties of OT-I CD8+ T cells in tumors and tdLNs." (PMID 38287103, 2024). "To determine whether ID2 promotes tumor growth in vivo, we transplanted long-term ID2-overexpressing PC3 cells and control cells into nude mice; the tumor volume growth curve showed that ID2 can increase the growth rate of PCa." (PMID 38254880, 2024). "ID2 expression in tumor-infiltrating CD8+ T cells was not affected by PDOX treatment in wild-type or CD43-deficient mice." (PMID 36796366, 2023). "We stained the tumor-infiltrating CAR T cells for TCF1, TBET, EOMES, GATA3, ID2, ID3 and IRF4." (PMID 37945901, 2023). "Our results signify that upregulation of Twist under Id2 knockdown may lead to HOXD10 reduction and probably block or reduce its tumor suppressor activities." (PMID 35982951, 2022). "Similarly, ID2 expression in DCIS-IPW cells rescued the number and size of spheres and tumor initiating stem cell population." (PMID 35078502, 2022). "Additionally, the expression of transcription factors known to promote tumor stemness (SOX2, OCT4 and NANOG) were significantly downregulated in DCIS cells expressing IPW and rescued when ID2 was expressed." (PMID 35078502, 2022). "Then, we clarified the roles of Id2 in LADC metastasis and tumor progression in vitro and in vivo." (PMID 35982951, 2022). "Ablation of Id2 in HSCs results in increased proliferation and HSC activation suggesting that ID2 may function as a tumor suppressor." (PMID 35990659, 2022).
tumor (continued). "In conclusion, lncRNA-LALR1 is highly expressed in HCC and promotes tumor growth and invasion by upregulating SNORD72 to stabilize ID2 mRNA, implying that lncRNA-LALR1 might be a novel target for intervention of HCC." (PMID 32160589, 2020). "ID2, which is elevated in cancer samples with defective DNA mismatch repair, and ID9 (of unknown aetiology) were significantly more pronounced in tumours with chromothripsis across all entities (p = 1.3 × 10−4 and 1.5 × 10−4, respectively, Wilcoxon tests)." (PMID 32385320, 2020). "Consistent with the gene expression profiling, ectopic expression of either Id2 or Aldh3a1 had no impact on the level of tumour burden in the lung but significantly increased tumour burden in the brain." (PMID 30642388, 2019). "Intriguingly, tumor cells with elevated surface Hsp90 expression (eHsp90hi) isolated from ARCaPE and DU145 demonstrated a profound increase in a cohort of stem-like effectors, such as Trop2, ID2 and Snail." (PMID 28038472, 2017). "In other mouse and human tumor cell lines Id2 was not dominant whereas Id1 and/or Id3 were (unpublished data)." (PMID 26079374, 2015). "None of the mice developed tumor at the site of Id2-kd N2a cell injection, while the growth of wild type tumor on the opposite leg was delayed when compared to control unvaccinated mice." (PMID 26079374, 2015). "Of interest, again none of the mice developed tumor at the site of Id2-kd N2a cell injection in this established tumor model." (PMID 26079374, 2015). "Tumor samples lacking ID2 deletions had intermediate levels of methylation." (PMID 40161734, 2025). "This study demonstrates that Id2-mediated transcriptional and epigenetic modification drives hierarchical CD8+ T-cell exhaustion, and the mechanistic insights gained may have implications for therapeutic intervention with tumor immune evasion." (PMID 38287103, 2024). "Likewise, we found increased expression of Id2 in tumor-infiltrating CD8+ T cells from patients with cancer, indicating that Id2 may be upregulated in activated T cells." (PMID 38287103, 2024). "Ablation of Id2 in HSCs results in increased proliferation, suggesting that ID2 may function as a tumor suppressor; however, we did not monitor the Id2Δ/Δ mice in these experiments beyond 12–16 weeks, when hematopoietic malignancies might develop." (PMID 35775482, 2022). "Id1, Id2 and Id3 may increase MMP gene expression, leading to tumor cell invasion." (PMID 28122577, 2017). "The effects described with Id2 targeting may or may not be expanded to other cell lines; research to determine applicability of this whole tumor cell vaccine strategy for other tumor types is underway." (PMID 26079374, 2015). "Although Id1, Id2 and Id3 were highly over-expressed in SCLC in our previous work, it is not known what exact roles they may play in SCLC cells and whether they can be used as a joint or separate treatment targets for tumor suppression." (PMID 25061504, 2014). "Further analyses revealed higher levels of both global and locus-specific L1 RNA expression in tumor tissues compared to normal tissues across all three major groups (EU_N, AS_N, and EU_S), as well as significantly higher expression in tumors with ID2 compared to those without ID2 (P = 0.021)." (PMID 40161734, 2025). "Taken together, these results demonstrate that the Tcf3-Tal1 complex dominates in the absence of the Id2 HLH domain and recruits LSD1 to alter chromatin accessibility at the Slamf6 promoter during the Texprog-to-Texterm conversion in tumor immune evasion." (PMID 38287103, 2024). "Among nine EBV-LMP1 totally negative tumours, four was positive for P16(INK4A) and also four positive for ID2." (PMID 19099554, 2008).
cancer (108 papers, 2004 to 2025). A tumor composed of atypical neoplastic, often pleomorphic cells that invade other tissues. "ID2 is found in most types of cancer, and a substantial number of variants with this signature has been reported in MMR-deficient / hypermutated malignancies." (PMID 34843512, 2021). "The ID gene family, including ID2, was found to be upregulated in various kinds of cancers, and ID2 in particular was associated with the development of several diseases." (PMID 33731118, 2021). "Other mutational signatures including SBS40, SBS5, ID9, ID1 and ID2 were also enriched in BRCA1/2-mutated cancers expressing high levels of wild-type POLQ." (PMID 32885167, 2020). "Among four types of Id proteins (Id1, Id2, Id3, and Id4), Id1 has been extensively studied in various cancers and is linked to tumorigenesis, as aberrant elevation of Id1 has been found in over 20 types of human cancer." (PMID 24970809, 2014). "Of all the four Id proteins, the expression of Id1, Id2, and to a lesser extent, Id3 in cancer and the underlying molecular mechanism is relatively well known." (PMID 23342267, 2012). "Aberrant ID2 expression is associated with poor prognosis in various cancers." (PMID 38195969, 2024). "ID1 and ID2 are characterised predominantly by insertions and deletions of single T bases at T mononucleotide repeats which are associated with strand slippage during DNA replication and are seen in most human cancers and normal tissues." (PMID 35803914, 2022). "Consistent with lucicebtide activity on C/EBPβ target genes in cancer cells, ID2, BIRC3, CyclinA2 and CDK1 were significantly downregulated in lucicebtide-treated M2-cells." (PMID 40103809, 2025). "Numerous studies have indicated that Id2 serves a unique function in modulating various inflammation‐cancer diseases." (PMID 40051059, 2025). "Most studies have indicated that Id2 effectively maintains the stemness of cancer cells, supporting their proliferation, migration and invasion." (PMID 40051059, 2025). "Knocking ID2 significantly inhibited cancer cell proliferation and invasion, while overexpressing ID2 enhanced these capabilities." (PMID 38195969, 2024). "Intriguingly, mutA3B (PC7) was also seen to inversely impact several mutational signatures across various cancers, particularly SBS1, SBS5, ID1, ID2, and ID7." (PMID 38965255, 2024). "In this study, we found that Id2 regulates the generation of Slamf6+ Texprog cells and the Texprog-to-Texterm conversion in cancer." (PMID 38287103, 2024). "Functional analysis, including CCK-8, colony formation, transwell, wound healing, and sphere formation experiments, were conducted to determine the biological functions of ID2 in human cancers." (PMID 38195969, 2024). "We observe that TRIM69 evokes, through degrading EYA4, nuclear β-catenin accumulation and transcription of Id2 gene, which had been reported to favor cancer progression via fostering mitosis, stem cell self-renewal and angiogenesis." (PMID 36741265, 2023). "This strongly implies that ID2 is a major player in nuclear GRP78 activities and functions, and the consequences are likely to be context dependent as ID2 is reported to play different roles in different cancers." (PMID 37487081, 2023). "On the NR0B2 cell trajectory of Abcb4−/− cholangiocytes, some molecules implicated in carcinogenesis were evidenced: GSTA3, ID2, and TMEM45A, which is a transmembrane molecule considered to be oncogenic in several cancers." (PMID 39130146, 2023). "Seminal studies have shown that Id2 can positively control proliferation of many cancer cell types in 2D, i.e. anchorage-dependent conditions." (PMID 35437308, 2022). "Id2 was prioritized because it is an established regulator of cancer proliferation and Rb-dependent cell cycle progression." (PMID 35437308, 2022). "Because the roles of Id2 differ depending on the cancer type, the determination of how Id2 affects LADC progression and metastasis is an urgent need." (PMID 35982951, 2022).
cancer (continued). "To date, many studies have investigated the functions of Id proteins in tumorigenesis in various cancers; however, Id2’s function in cancer is still unclear." (PMID 35982951, 2022). "The expression of MMP2 is regulated by the ID2 and ID2 promotes cell migration and invasion in different types of human cancer cells." (PMID 35705978, 2022). "Meanwhile, seven common genes, FOSL1, S100A9, CXCL12, ID2, PRS6KA3, AREG, and DUSP6, have been used as the target biomarkers and even the diagnostic tools in cancer therapy." (PMID 34490085, 2021). "In cancer cells, Id2 proteins antagonize the Rb family of cell cycle inhibitors, thereby allowing progression from G1 to S phase of the cell cycle." (PMID 31882403, 2020). "In other cancers, the ID2 protein promotes early-stage progression and survival during metabolic stress, and its defect leads to a more differentiated less aggressive phenotype." (PMID 33473258, 2020). "Results demonstrated that after verification at the transcriptional and translational levels in four different cancer cells, ID2 was identified as an ATO anti-tumor-connected protein." (PMID 30634536, 2019). "Two differentially expressed genes, Id2 and Aldh3a1, were validated in in-vivo models using mouse and human cancer cell lines." (PMID 30642388, 2019). "Consistent with earlier studies, this study indicated that PA increase is associated with up-regulation of ID1, ID2, and ID3 mRNA expression and therefore inhibition of cancer cell differentiation." (PMID 30455990, 2018). "Following our in vitro experiments, we investigated the in vivo efficacy of the Id2 knockdown on cancer-cell dissemination using a mouse model." (PMID 26965643, 2016). "The BMP signaling pathway is a potent direct regulator of the transcription of Id1, Id2, and Id3 during development as well as in cancer cells." (PMID 27048361, 2016). "Cyclin D1 (CCND1), c-MYC, and DNA-binding protein inhibitor ID-2 (ID2) genes encode proteins strictly involved in cell proliferation and cancer development." (PMID 26450900, 2015). "Id2 mediates mitogenic signals, inhibits differentiation and plays a critical role in cancer development and metastasis." (PMID 24376712, 2013). "Our results demonstrating a different role of Id1 and Id2 in ACCM cells suggest that SGCs differ from other types of cancer in which Id1 and Id2 appear to play a more equivalent role." (PMID 23517130, 2013). "Ectopic expression of the wild-type human Id2 markedly increased the in vitro invasion capacity of MCF-7 and SKOV-3 cancer cells, which was further augmented by transfection with the degradation-resistant form of Id2." (PMID 19257909, 2009). "When Id2 is overexpressed in A549 carcinoma cells, there is a decrease in cyclin A promoter activity compared to control cells." (PMID 19609365, 2009). "METTL3 May posttranscriptionally upregulate the levels of inhibitor of DNA binding 2 (ID2) in an m6A/YTHDF2-dependent mechanism, thereby enhancing ID2 mRNA stability and promoting cancer cell proliferative capacity." (PMID 40986143, 2025). "The TCGA database were utilized to explore the clinical relevance of ID2 in cancer." (PMID 38195969, 2024). "Our work identifies Id2 as a novel transcriptional regulator of CD8+ T-cell exhaustion in cancer." (PMID 38287103, 2024). "Related research suggests that ID2 may be dysregulated and play varying roles in the progression of several cancer types." (PMID 38195969, 2024). "GO, KEGG, and TIMER were employed to predict the potential roles of ID2 in cancer." (PMID 38195969, 2024). "ID2 has been shown to mediate the expression of MMP2 in cancer cells." (PMID 35705978, 2022). "As toyocamycin was shown to inhibit the ID2-dependent cancer stem cell enrichment, we speculate that this compound could be of immense value for the clinical use where DCIS patients are generally over treated to prevent its progression to the invasive forms." (PMID 35078502, 2022).
cancer (continued). "In addition, outside those mentioned, a group of transcription factors, which dysregulation has been widely associated with cancer phenotype was identified, including DEGs such as BCL6, DDIT3, GADD45A, HMGA2, and ID2." (PMID 35359411, 2022). "Similarly, ID2 expression in cancer is also correlated with self-renewal ability and resistance to chemotherapy, suggesting the significance of miR-29c and ID2 axis in cancer." (PMID 35078502, 2022). "Conform our scRNA-seq findings, microvascular ECs exclusively expressing FABP4 or ID2 could be identified in human breast (cancer) tissue." (PMID 36127427, 2022). "Bioinformatics analysis revealed that these effects of Id2 on cancer progression might be regulated by focal adhesion kinase (FAK) signaling and CD44/Twist expression." (PMID 35982951, 2022). "Moreover, transient overexpression of ID2 in the parental H23 cell line also represses cancer invasion." (PMID 32751497, 2020). "New small molecule activators or inhibitors of ID2:DNA clamping could be therapeutics in FA or cancer-treatment." (PMID 32167469, 2020). "Other mutational signatures including SBS40, SBS5, ID9, ID1 and ID2 were not significantly enriched more in BRCA1/2-mutated cancers expressing wild-type POLQ than in other types of cancers." (PMID 32885167, 2020). "Emerging functions for ID2 in regulating energy metabolism may provide insights into pathways that could be targeted for cancer therapy." (PMID 28206987, 2017). "ID2 plays dual roles in different cancer types which may attribute to tissue-specific patterns of expression in different tissues and organs in tumourigenesis." (PMID 29190891, 2017). "The impact of ID2 expression on clinical outcome has been revealed in human cancers." (PMID 29190891, 2017). "ID2 is an important mediator of both plasma cell differentiation and induction of apoptosis and the ID signaling pathway has previously been reported to be deregulated in cancer." (PMID 26755663, 2016). "Overall, in cancer-associated or cancer-adjacent gastric myofibroblasts Dies1 is overexpressed, however the expression of its potential downstream targets, ID2 and ID3, does not follow the same trend." (PMID 27721458, 2016). "Id1 and/or Id3 may be better targets in other cancer types for inducing the attenuated, immunogenic effect observed following Id2 knock down in Neuro2a cells." (PMID 26079374, 2015). "Since the Inhibitors of DNA binding/differentiation (Id) family members are direct mediators of the BMP signaling, and they are involved in invasion, proliferation and metastasis of cancer cells, we measured the gene expression of Id1, Id2 and Id3 in A549 by qPCR." (PMID 24603907, 2014). "After onset of other oncogenic events, reduced Id-2 expression might increase aggressiveness of ESCC cancer cells through dedifferentiation and leads to poor patient survival." (PMID 18000500, 2007). "We have asked whether functional Id2 expression is necessary for Wnt induced mammary hyperplasia, side branching, and cancer, by generating mice expressing a Wnt1 transgene in an Id2 mutant background." (PMID 15601467, 2004). "We have asked therefore whether functional Id2 expression is necessary for Wnt induced mammary hyperplasia, side branching and cancer, by generating mice expressing a Wnt1 transgene in an Id2 mutant background." (PMID 15601467, 2004). "It has been proposed that Wnt signaling may inhibit differentiation and promote the maintenance of a proliferative state by increasing Id2 expression, thereby leading to cancer." (PMID 15601467, 2004). "Additionally, ID2 mediates resistance of cancer cells to protein kinase B (or Akt) inhibitions." (PMID 38195969, 2024). "Moreover, ID2 plays a crucial role in regulating cancer immune responses." (PMID 38195969, 2024).